MATR3 (matrin 3)
Description:
May play a role in transcription or may interact with other nuclear matrix proteins to form the internal fibrogranular network. In association with the SFPQ-NONO heteromer may play a role in nuclear retention of defective RNAs. Plays a role in the regulation of DNA virus-mediated innate immune response by assembling into the HDP-RNP complex, a complex that serves as a platform for IRF3 phosphorylation and subsequent innate immune response activation through the cGAS-STING pathway. Binds to N6-methyladenosine (m6A)-containing mRNAs and contributes to MYC stability by binding to m6A-containing MYC mRNAs. May bind to specific miRNA hairpins.
Synonyms: KIAA0723; MGC9105; VCPDM; ALS21; MPD2
Tractability: PROTAC: UniProt records ubiquitination sites on it; ubiquitination databases record sites on it; its protein half-life has been measured.
Gene: Protein-coding gene on chromosome 5 (139,273,752 to 139,331,677, forward strand). Ensembl gene ENSG00000015479.
Subcellular location: Nucleus matrix
Subcellular location (Human Protein Atlas): Nucleoplasm
Gene Ontology:
Molecular function: identical protein binding; miRNA binding; protein binding; RNA binding; structural molecule activity; nucleic acid binding; zinc ion binding
Biological process: activation of innate immune response; post-transcriptional regulation of gene expression; heart valve development; ventricular septum development
Cellular component: membrane; nuclear inner membrane; nuclear matrix; nucleus
Genetic constraint (gnomAD): Loss-of-function variants: 4 observed, 74.85 expected, observed/expected ratio (o/e) 0.0534, 90% interval 0.025 to 0.12. The upper end of that interval is the gene's LOEUF score, 0.12, which puts it in group 1 of 6, group 1 being the genes least tolerant of losing a copy. Missense variants: 647 observed, 987.33 expected, observed/expected ratio (o/e) 0.66, 90% interval 0.61 to 0.7. Synonymous variants: 316 observed, 335.08 expected, observed/expected ratio (o/e) 0.94, 90% interval 0.86 to 1.03.
Gene-disease validity (ClinGen):
ClinGen rates the evidence that MATR3 causes each of these diseases.
distal myopathy with vocal cord weakness (autosomal dominant): Definitive. Distal myopathy with vocal cord and pharyngeal weakness is an adult-onset, autosomal dominant muscular disease which is characterized by muscle weakness in the feet and hands, combined with vocal or swallowing dysfunction.
Homologues: Orthologues: chimpanzee MATR3 (99% identical), macaque MATR3 (99% identical), pig MATR3 (99% identical), rabbit MATR3 (99% identical), guinea pig MATR3 (99% identical), dog MATR3 (98% identical), mouse Matr3 (98% identical), rat Matr3 (96% identical), tropical clawed frog matr3 (57% identical). Paralogues in human: ZNF638 (26% identical).
Diseases named in the same sentence as MATR3 in open-access papers:
MATR3 is named in the same sentence as 83 diseases in open-access papers, as found by Europe PMC text mining. Sharing a sentence is not in itself a finding about the gene and the disease. The quoted sentences say what the papers report.
amyotrophic lateral sclerosis (32 papers, 2015 to 2024). Amyotrophic lateral sclerosis (ALS) is a neurodegenerative disease characterized by progressive muscular paralysis reflecting degeneration of motor neurons in the primary motor cortex, corticospinal tracts, brainstem and spinal cord. "Recent research has sparked a discussion on the spectrum of diseases linked to the MATR3 gene associated with amyotrophic lateral sclerosis and distal myopathy with vocal cord and pharyngeal weakness (VCPDM)." (PMID 39192891, 2024). "It is known that certain genes analyzed in our study have variants associated with other diseases in addition to MDs; for example, MATR3 is associated with Amyotrophic Lateral Sclerosis 21 and LMNA is associated with Hutchinson-Gilford Progeria Syndrome." (PMID 38755190, 2024). "Heterozygous variants in the MATR3 gene cause amyotrophic lateral sclerosis (ALS) type 21 and distal myopathy with vocal cord and pharyngeal weakness (VCPDM) inherited in autosomal dominant manner." (PMID 39192891, 2024). "Diseases associated with MATR3 include amyotrophic lateral sclerosis 21 and distal myopathy with vocal cord weakness." (PMID 37019990, 2023). "Fibroblasts from an amyotrophic lateral sclerosis patient with simultaneous mutations in the MATR3 gene and KIF5A gene were isolated and reprogrammed into induced pluripotent stem cells via a non-integrating Sendai viral vector." (PMID 33388707, 2021). "Missense mutations in MATR3 including S85C, F115C, P154S, and T622A have been associated with a rare human disorder called Amyotrophic lateral sclerosis (ALS)." (PMID 32977861, 2020). "In the module 2, MATR3, known as a vital pathogenic gene of amyotrophic lateral sclerosis, is still poorly understood in the process of cancerization." (PMID 32802855, 2020). "A missense mutation, S85C, in the MATR3 gene is a genetic cause for amyotrophic lateral sclerosis (ALS)." (PMID 33082323, 2020). "Next generation sequencing of a panel of 28 genes associated with dementia and amyotrophic lateral sclerosis (ALS) initially revealed a duplication of exon 15 in Matrin-3 (MATR3)." (PMID 33408686, 2020). "Mutations in the matrin 3 gene are linked with familial forms of amyotrophic lateral sclerosis, suggesting an important role in neuroprotection." (PMID 32749514, 2020). "Mutations in MATR3 have been associated with amyotrophic lateral sclerosis (ALS) as well as a form of distal myopathy termed vocal cord pharyngeal distal myopathy (VCPDM)." (PMID 30563574, 2018). "Mutations in the intrinsically disordered regions of a number of RBPs, including MATR3, can lead to neuronal death in amyotrophic lateral sclerosis, and these mutations often change the dynamics of RNP assembly." (PMID 30078707, 2018). "Moreover, mutation of MATR3 is responsible for distal myopathies and amyotrophic lateral sclerosis in humans." (PMID 29481576, 2018). "Most notably, missense mutations in MATR3 have been linked to amyotrophic lateral sclerosis (ALS), a fatal neurodegenerative disease caused by the loss of motor neurons, as well as in neurodevelopmental diseases." (PMID 38891112, 2024). "Mutations in MATR3 have been linked to amyotrophic lateral sclerosis (ALS), a devastating adult-onset neurodegenerative disease that is characterized by the loss of motor neurons, leading to muscle atrophy, paralysis, and death." (PMID 38891112, 2024). "MATR3, which is also bound by the third motif, is a member of a subset of RBPs that have been linked to both sporadic and familial neuromuscular disease as well as to muscular and neurodegenerative diseases such as amyotrophic lateral sclerosis (ALS) and frontotemporal dementia (FTD)." (PMID 37446229, 2023). "The potential role of Matr3 in RNA metabolism has received support from studies of amyotrophic lateral sclerosis (ALS), a neurodegenerative disorder with diverse underlying genetics." (PMID 34716321, 2021).
amyotrophic lateral sclerosis (continued). "To understand how mutations in Matrin 3 (MATR3) cause amyotrophic lateral sclerosis (ALS) and distal myopathy, we used transcriptome and interactome analysis, coupled with microscopy." (PMID 29511296, 2018). "Mutations in Matrin 3 [MATR3], an RNA- and DNA-binding protein normally localized to the nucleus, have been linked to amyotrophic lateral sclerosis (ALS) and distal myopathies." (PMID 26528920, 2015). "Moreover, sequencing studies of patients revealed a handful of disease-associated mutations in MATR3 linked to amyotrophic lateral sclerosis (ALS), which further elevated the gene’s importance as a topic of study." (PMID 38891112, 2024). "One candidate’smother had MATR3-related amyotrophic lateral sclerosis 21, anadult-onset autosomal dominant disorder, and another candidate ́s mother had aneurological disorder under investigation." (PMID 35916466, 2022). "Further, it has been reported that ZC3H11A associates with a mutant version of the nuclear matrix protein, Matrin-3, which has been found in patients with amyotrophic lateral sclerosis (ALS)." (PMID 33217981, 2020). "So far, MATR3’s role has been relatively well studied in Amyotrophic lateral sclerosis (ALS), a rare human genetic disorder." (PMID 32977861, 2020). "In addition, MATR3 has been widely studied in amyotrophic lateral sclerosis." (PMID 36570001, 2022). "Few years after the first association of VCPDM to MATR3 gene, several mutations in the same gene, including p.S85C, were found to be causative of familial amyotrophic lateral sclerosis (ALS)." (PMID 34659085, 2021). "Genetic analyses of patients with amyotrophic lateral sclerosis (ALS) have revealed a strong association between mutations in genes encoding many RNA-binding proteins (RBPs), including TARDBP, FUS, hnRNPA1, hnRNPA2B1, MATR3, ATXN2, TAF15, TIA-1, and EWSR1, and disease onset/progression." (PMID 32547363, 2020). "A number of neuromuscular and muscular diseases, including amyotrophic lateral sclerosis (ALS), spinal muscular atrophy (SMA) and several myopathies, are associated to mutations in related RNA-binding proteins (RBPs), including TDP-43, FUS, MATR3 or hnRNPA1/B2." (PMID 32292882, 2020). "In addition, ZC3 has been reported to interact with a mutant form of the nuclear matrix protein Matrin-3, which is present in amyotrophic lateral sclerosis (ALS) patients." (PMID 38033582, 2023). "Mutations affecting several RBPs, including FUS, TDP-43, hnRNPA1, hnRNPA2B1, matrin-3, and TIA1, are linked to amyotrophic lateral sclerosis (ALS), frontotemporal dementia (FTD), multisystem proteinopathy (MSP), and hereditary inclusion body myopathy (hIBM) phenotypes." (PMID 34291734, 2021). "Clinically Matrin 3 has been linked as a cause of the neurodegenerative disease familial amyotrophic lateral sclerosis (ALS), interacting with the RNA binding protein TDP-43, a protein that when mutated is known to cause ALS." (PMID 26129669, 2015).
distal myopathy (19 papers, 2015 to 2024). Distal myopathy refers to a group of muscle diseases which share the clinical pattern of predominant weakness and atrophy beginning in the feet and/or hands. "In this study, we present a case series of distal myopathy associated with the heterozygous previously reported p.S85C variant in the MATR3 gene." (PMID 39192891, 2024). "Our observations include patients exhibiting both the typical phenotype associated with MATR3-related distal myopathy and rare symptomatic manifestations of the disease." (PMID 39192891, 2024). "For instance, VCP, hnRNPA1, and hnRNPA2B1 mutations cause multisystem proteinopathy with Paget’s disease of bone, inclusion body myopathy, ALS, and FTD; TIA1 and MATR3 mutations result in distal myopathy in addition to ALS and FTD." (PMID 33427209, 2021). "Since 2009, p.S85C mutation in MATR3 gene is known to be causative of an autosomal dominant form of distal myopathy with vocal cord and pharyngeal weakness (VCPDM)." (PMID 34659085, 2021). "MATR3 was first implicated in human disease in an American family with an autosomal dominant form of distal myopathy with VCPDM." (PMID 33427209, 2021). "Mutations in the MATR3 gene are associated to distal myopathy with vocal cord and pharyngeal weakness (VCPDM), as well as familiar and sporadic motor neuron disease." (PMID 34659085, 2021). "In this study, a comprehensive pattern of muscular involvement in MATR3-associated distal myopathy has been established." (PMID 32361838, 2020). "Studies using whole-body MRI are missing for most of the distal myopathies with relevant congruency to MATR3-associated myopathy." (PMID 32361838, 2020). "Matrin-3-associated distal myopathy is a rare late-onset distal myopathy predominantly affecting the lower legs as well as finger and wrist extensors." (PMID 32361838, 2020). "On the basis of the available literature, patterns of gluteal and paraspinal affection found in MYOT-associated distal myopathy were divergent to the findings in MATR3-myopathy." (PMID 32361838, 2020). "Another distal myopathy that has been associated to defects in ISR is Matrin-3-associated distal myopathy (MATR3-myopathy)." (PMID 32823799, 2020). "In this study, whole body-MRI scans of patients with genetically proven Matrin-3-associated distal myopathy were used with the aim to identify a specific pattern of muscular affection and to monitor the sequence of involvement." (PMID 32361838, 2020). "Muscle MRI of patients with MATR3-associated distal myopathy revealed a distinct pattern of muscular involvement." (PMID 32361838, 2020). "MATR3-associated distal myopathy is a rare distal myopathy predominantly affecting lower legs as well as wrist- and finger extensors." (PMID 32361838, 2020). "First, a MATR3 missense mutation p.Ser85Cys (chr5:138643358, C>G) was associated with vocal cord and pharyngeal weakness with distal myopathy (weakness and atrophy of the hands and feet)." (PMID 32292882, 2020). "In this regard, the only available publication addressing whole-body MRI in MATR3-associated distal myopathy apart from the present study is a case report describing one french patient." (PMID 32361838, 2020). "In summary, the distinct pattern of muscular affection established in this study expands the diagnostic opportunities in MATR3-associated distal myopathy in terms of discrimination to other distal myopathies." (PMID 32361838, 2020). "S85C mutations in Matrin 3 have also been linked to vocal cord and pharyngeal weakness with distal myopathy (VCPDM), a progressive autosomal dominant distal myopathy that also results in dysphagia, dysphonia and vocal cord and pharyngeal weakness." (PMID 29109432, 2017). "For example, familial ALS and distal myopathy were associated with mutations in MATR3." (PMID 35559016, 2022).
distal myopathy (continued). "Since spinal cord and skeletal muscle are pathologically affected in ALS and distal myopathy, the low levels of MATR3 in adults could suggest that these two tissues are peculiarly susceptible to alterations in MATR3 function." (PMID 33357424, 2020). "While pathogenic mutations in the DNA/RNA-binding protein Matrin-3 (MATR3) are linked to ALS and distal myopathy, the molecular mechanisms underlying MATR3-mediated neuromuscular degeneration remain unclear." (PMID 32811564, 2020). "Thus, the aim of the present study was to establish a disease-specific pattern of muscular involvement in MATR3-associated distal myopathy using whole-body MRI." (PMID 32361838, 2020). "Additionally, gluteal and paraspinal changes as observed in MATR3-myopathy were not seen in whole-body examination of a patient with SQSTM1/TIA1-associated distal myopathy, a distal myopathy that displays similar lower limb findings as compared to MATR3-associated myopathy." (PMID 32361838, 2020). "Furthermore, different mutations in MATR3-related disease may cause either ALS or distal myopathy, and dementia/lower motor neuron syndrome can coexist with myopathies due to VCP mutations (OMIM #167320)." (PMID 26999347, 2016). "Among the six cases reported here, two exhibited a scapuloperoneal phenotype of MATR3-related distal myopathy, necessitating differential diagnosis with FSHD in one of the cases." (PMID 39192891, 2024). "Here, we summarize the current understanding of matrin 3 (MATR3), a poorly understood RBP implicated not only in ALS and frontotemporal dementia but also in distal myopathy." (PMID 33427209, 2021). "When comparing the MATR3-pattern to literature-based patterns of other distal myopathies, a good distinction to most of the disease entities was seen." (PMID 32361838, 2020). "MATR3-myopathy is a distal myopathy clinically characterized by weakness of foot dorsiflection, finger and wrist extension, as well as early axial affection." (PMID 32823799, 2020). "The crucial remaining question is how mutations in MATR3 lead to disease pathogenesis of ALS/FTD and distal myopathy." (PMID 32811564, 2020). "A relevant discrimination (e.g. mismatch > 20%) of the MATR3-pattern to the majority of distal myopathies (16 out of 22 disease entities) was seen." (PMID 32361838, 2020). "Especially, heterozygous mutations in MATR3 are known to cause ALS type 21 (ALS21), which is characterized by vocal cord weakness and pharyngeal dysfunction with distal myopathy." (PMID 32977861, 2020). "MYOT-myopathy usually presents with a myofibrillar histopathology, that has not been identified in MATR3-associated distal myopathy." (PMID 32361838, 2020). "While TIA1- and SQSTM1/TIA1-associated distal myopathy display a rather identical clinical phenotype compared to MATR3 (in terms of onset, muscle weakness and histopathology), none of these disease entities typically include a relevant dysphagia and dysphonia." (PMID 32361838, 2020). "Since its first description as Vocal cord and pharyngeal weakness with distal myopathy (VCPDM) in 1998 and subsequent identification of the causative mutation in the MATR3-Gene (p.S85C, c.254C > G), a number of patients with Matrin-3-associatied distal myopathy have been identified." (PMID 32361838, 2020). "Our findings in these cell culture experiments suggest that mutations in Matrin 3 that cause fALS or, in some cases distal myopathy, do not produce obvious changes in its subcellular localization." (PMID 26528920, 2015). "Given the multiple potential functions of Matrin 3, sorting out which function may be involved in causing ALS, or distal myopathy, will be challenging." (PMID 26528920, 2015). "It was interesting that both the spinal cord and muscle had such low levels of MATR3, given that they are pathologically affected in ALS or distal myopathy." (PMID 30563574, 2018).
distal myopathy (continued). "Our data suggest that MATR3-linked diseases may lie on a spectrum between ALS and distal myopathy, and this spectrum is not without precedent." (PMID 30563574, 2018).